CRP (C-reactive protein)
Diseases named in the same sentence as CRP in open-access papers (continued):
Sharing a sentence is not in itself a finding about the gene and the disease.
COVID-19 (continued). "In practice, this meant that antibiotics were not prescribed even for patients with high serum biomarkers for infection, such as C-reactive protein or procalcitonin, as the specificity of the two was not good enough to predict secondary bacterial pneumonia in COVID-19 patients." (PMID 39596728, 2024). "Furthermore, it was found that levels of C-reactive protein (CRP), a component known to induce the output of proinflammatory cytokines, apoptosis and inflammation, have a positive correlation with the severity of COVID-19." (PMID 39769125, 2024). "In addition, Vietnamese research showed that the affected COVID-19 individuals (regardless of the disease’s stage) presented with increased CRP levels." (PMID 38675414, 2024). "Similarly, critical COVID-19 patients with infections had modestly higher CRP levels (p = 0.046) than non-infected patients." (PMID 39273246, 2024). "Additionally, the acute phase proteins (CRP, SAA1 and SAA2) deviated from the linear correlation (R2 = 0.97) of the plasma proteome changes quantified in both genders, indicating a 3- to 6-fold difference in concentrations measured six months after COVID-19." (PMID 39183264, 2024). "COVID-19 patients with cardiac injury had a higher CRP level than patients without cardiac injury." (PMID 37712883, 2024). "Higher levels of neutrophils, lymphocytes, monocytes, and CRP and lower levels or the absence of eosinophils were detected in the patients with COVID-19+ as compared to the control group and those with asymptomatic COVID-19 (p < 0.05)." (PMID 39311307, 2024). "The significant direct correlation of pericardial effusion with CRP levels may suggest that pericardial inflammation, but not cytokine storm, may play an important part in the development of this complication in COVID-19 patients." (PMID 38999316, 2024). "Furthermore, this study revealed a negative correlation between CRP, ferritin, D-dimer, and the percentage of lymphocytes in COVID-19 patients, which is consistent with existing literature." (PMID 39407725, 2024). "Interestingly, there was minimal difference in CRP levels between the COVID-19 negative and COVID-19 positive samples." (PMID 38879593, 2024). "As COVID-19 severity increased, there were corresponding rises in infection indicators like white blood cell (WBC) count, neutrophil to lymphocyte ratio (NLR), C-reactive protein (CRP), serum amyloid A (SAA), and inflammatory mediators such as interleukin-6 (IL-6) and interleukin-10 (IL-10)." (PMID 39081794, 2024). "Higher levels of inflammatory markers, including C-reactive protein (CRP) and the neutrophil-to-lymphocyte ratio, as well as various inflammatory cytokines and chemokines, have been shown to be related to a more severe clinical course in patients with COVID-19." (PMID 37623485, 2023). "A total of 64.3% of the patients had an acute COVID-19 condition of mild/moderate severity, and the remaining 35.7% suffered a severe condition requiring hospital admission, with expected alterations in the admission analysis (elevated levels above AST, ALT, CRP, D-dimer, and IL-6 reference values)." (PMID 37515140, 2023). "IL-6, neutrophil count, % neutrophils, NLR, PLR, CRP, AST, and urea rose with the increased severity of the SARS-CoV-2 infection, and lymphocyte count, % lymphocytes, eosinophil count, % eosinophils, hemoglobin decreased with the increased severity of COVID-19." (PMID 36838284, 2023). "Similarly, elevated CRP, LDH, and ferritin are all markers of the inflammatory process in COVID-19." (PMID 37041917, 2023). "According to other systematic reviews, high blood White Blood Cell count (WBC), high blood aspartate aminotransferase (AST), high blood C-reactive protein (CRP), low blood platelet count, and a decrease in lymphocyte count may increase the possibilities of severe COVID-19 symptoms." (PMID 38249981, 2023).
COVID-19 (continued). "Biomarkers such as CRP and individual CBC parameters (EOS# and PLT), measured before any treatment that could interfere with laboratory results, may be predictive of the severe form of COVID-19, with the need for hospitalization and oxygen therapy later on." (PMID 37570378, 2023). "There were significant differences in neutrophil, lymphocyte, eosinophil (Eos), C-reactive protein (CRP), D-dimer, lactate dehydrogenase (LDH), glucose, IL-6, ferritin, CD4 + T cell, CD4+/CD8 + T cell, CD8 + T cell, and B cell counts in the serum of the four COVID-19 patient groups (P < 0.05)." (PMID 37705107, 2023). "Regarding detection of infiltrate above median compared to infiltrate below median in COVID-19, multivariate stepwise binary logistic regression analyses adjusted for the potential confounding variables were performed separately for each DPP3, IL-6, CRP, and leucocytes." (PMID 37733154, 2023). "This study identified significant predictors for COVID-19 severity, including older age, presence of chronic disease, high WBC count, high neutrophil count, low lymphocyte count, low hemoglobin, high D-dimer, high CRP, high ferritin, high troponin T, high creatinine, low albumin, and high ALP." (PMID 38130539, 2023). "Also, measurements of plasma inflammatory markers such as ferritin, C-reactive protein (CRP) and procalcitonin (PCT) could be used to predict COVID-19 progression." (PMID 37790205, 2023). "SPC was decreased in normotensive COVID-19 patients compared to the cohort without COVID-19 and therefore did not stand out as significant in this comparison, same for the laboratory value CRP, which was increased in normotensive and hypertensive COVID-19 patients." (PMID 37845506, 2023). "At the biochemical level, COVID-19 patients had decreased serum levels of albumin, alanine aminotransferase (ALT), aspartate aminotransferase (AST), LDH, highly sensitive troponin (hs-troponin), procalcitonin, serum ferritin, procalcitonin, elevated triglycerides, and CRP." (PMID 36851766, 2023). "In our study, despite increased CRP levels in more severe forms of periodontitis and COVID-19, none of the adjusted statistical models could meaningfully account for the observed differences." (PMID 37568161, 2023). "Furthermore, the markers of COVID-19 severity, such as CRP, LDH, D dimer and ferritin were not significantly different between the two groups." (PMID 37948563, 2023). "However, our study showed a reduced level of inflammatory markers called D-dimer and CRP and increased oxygenation (PaO2/FiO2 ratio), indicating that NAC may positively affect COVID-19 severity." (PMID 37534078, 2023). "Moreover, FMD continues to correlate to COVID-19 severity also after 3 months, unlike CRP measurement." (PMID 37626735, 2023). "In addition to the findings in COVID-19 patients without T2D, the study also investigated the correlation between gut microbiota and CRP and LoS in COVID-19 patients with T2D." (PMID 36844398, 2023). "Furthermore, we found that CRP levels were greater in COVID-19 ICU patients than in non-ICU patients." (PMID 36747045, 2023). "In another uncontrolled exploratory study in 77 patients with moderate COVID-19, treatment with nebulized IFN-a2b significantly reduced the duration of detectable virus in the upper respiratory tract and in parallel reduced duration of elevated blood levels for the inflammatory markers IL-6 and CRP." (PMID 38077399, 2023). "In clinical chemistry, C-reactive protein (CRP), procalcitonin (PCT), interleukin-6 (IL-6), and ferritin are known biomarkers that are elevated in the setting of acute inflammation and may help predict an unfavorable outcome in COVID-19." (PMID 37937220, 2023). "But, the prescription of berberine (900 mg, daily, 14 days) to patients with severe COVID-19 could not affect CRP levels." (PMID 37654997, 2023).
COVID-19 (continued). "However, the percentage of parameters with altered levels in terms of CRP was higher in the without-COVID-19 groups (ward: 40%; ICU: 20%) than in the with-COVID-19 groups (ward: 27.1%; ICU: 14.7%)." (PMID 37510647, 2023). "The present study demonstrated that both CRP and NLR on admission can, as individual biomarkers, differentiate COVID-19 alone from COVID-19 with bacteraemia, and was the first to investigate the cut-off value of CRP and NLR for predicting bacteraemia in COVID-19." (PMID 37939245, 2023). "Elevated levels of inflammatory biomarkers such as serum D-dimer (24.46%), CRP (32.18%),ferritin (26.60%), ESR (4.3%), LDH (8.6%), blood urea nitrogen (17.2%), creatinine (9.01%), and random blood sugar (RBS)>140 mg/dl (24.03%) were found inthe hospitalized patients with COVID-19." (PMID 37928498, 2023). "Finally, we identified certain parameters such as Interleukin (IL)-6 concentration, C reactive protein (CRP) level and platelet count that allowed to discriminate between death and survival in patients hospitalized with severe COVID-19 only during the first wave." (PMID 36817433, 2023). "Experimental CRP-targeting strategies have been suggested and investigated in numerous indications, including cardiovascular incidents (AMI, ischemic stroke), hyperinflammatory settings (COVID-19, pancreatitis) and autoimmune diseases (rheumathoid arthritis, Crohn’s disease)." (PMID 37626775, 2023). "Patients with co-infections or secondary infections had higher levels of white blood cells, neutrophils, blood urea nitrogen, lactate dehydrogenase, serum ferritin, Krebs-von-den-Lungen-6, C-reactive protein, and procalcitonin (all P < 0.0001) than COVID-19 patients without bacterial infections." (PMID 37101265, 2023). "Hence, the two-gene-signature CLEC12A and ACHE could provide an accurate tool for stratifying COVID-19 patients already upon ICU admission and at least one week earlier than CRP, PCT, and SOFA." (PMID 36928077, 2023). "It has been shown previously that the level of variation in the laboratory results of COVID-19 patients is different among many studies, Here, it was observed that the levels of D-dimer, LDH, renal profile and Inflammatory markers, such as ferritin, CRP, and troponin were outside the normal range." (PMID 37199912, 2023). "Both groups showed elevated levels of CRP+ EVs, with 55% (CI 46–61%) and 62% (CI 40–68%) CRP+ EVs in COVID-19 negative and COVID-19 positive patients, respectively, confirming previous results, while only 4% (CI 2–4%) of all EVs were associated with CRP in healthy controls." (PMID 36980378, 2023). "The study used chi-squared and t-test to find significant differences in gut bacteria between samples and non-parametric correlation analysis to examine relationship between gut bacteria abundance, C‐reactive protein (CRP) levels and length of stay (LoS) in COVID-19 patients without T2D." (PMID 36844398, 2023). "As IL-6, CRP, NLR, PLR, lymphocyte count, and eosinophil count are strongly correlated with the form of the disease, we can state that they may represent a minimum set of markers to be tested as the best predictors for the aggressive evolution of COVID-19." (PMID 36838284, 2023). "Numerous laboratory investigations, such as D-dimer, c-reactive protein (CRP), lactate dehydrogenase (LDH), ferritin, procalcitonin (PCT), and cytokine assays, especially interleukin-6 (IL-6), have been investigated for their prognostic and therapeutic role in COVID-19 patients." (PMID 38074058, 2023). "COVID-19 positive and negative patient samples were monitored for CRP levels." (PMID 37364815, 2023). "DPP3 (ρ = 0.46, p < 0.001), CRP (ρ = 0.67, p < 0.001), and leucocytes (ρ = 0.39, p < 0.001) were significantly correlated with pulmonary infiltrates in COVID-19 patients, as opposed to non-COVID-19 patients (each p = n.s)." (PMID 37733154, 2023).
COVID-19 (continued). "When outcome was determined according to the WHO clinical progression scale, patient age of older than 75 years, high CRP, high LDH, AEP, high neutrophil-to-lymphocyte ratio (NLR), and the presence of pulmonal comorbidities were significant independent predictors for severe COVID-19." (PMID 37766326, 2023). "Considering all COVID-19 patients in terms of hospital admissions, positive correlations between the plasma levels of MMP-9 and WBC absolute count (ρ = 0.4794, p < 0.0001), N absolute count (ρ = 0.5403, p < 0.0001), NLR (ρ = 0.4261, p < 0.0001) and CRP (ρ = 0.2335, p = 0.0132) were found." (PMID 37509076, 2023). "Serial CRP, WBC count, and platelet count are readily available in clinical practice and provide additional predictive value for disease progression and clinical outcomes, supporting the use of serial laboratory biomarkers in the triage and monitoring of hospitalized patients with COVID-19." (PMID 37934759, 2023). "However, missing from the literature until now has been an adjudication of the relative performance of LCR as compared to CRP for predicting mortality and other serious adverse outcomes (such as intubation and ICU requirement) in acute COVID-19; this study provides such head-to-head comparison." (PMID 37373898, 2023). "Thus, IL-6 concentration, C reactive protein level and platelet count allowed to discriminate between death and discharge in patients hospitalized with severe COVID-19 only during the first but not the second wave." (PMID 36817433, 2023). "Firstly, the observed correlations between gut microbiota diversity and clinical parameters such as LoS, CRP, and NLR in COVID-19 patients with T2D suggest that monitoring gut microbiota diversity may serve as a non-invasive biomarker for disease severity and the response to treatment." (PMID 37375851, 2023). "He had not left hospital until his COVID-19, evaluated by CRP and RT-qPCR, was controlled." (PMID 36774503, 2023). "Changes in CRP levels before and during COVID-19 were not significantly different." (PMID 38136035, 2023). "We did not observe statistically significant differences in CRP and D-dimer parameters between the control group and the study group, in patients before and after the antidepressant treatment as well as their history of COVID-19." (PMID 38002663, 2023). "In previous literature, it was stated that some indicators such as highly sensitive CRP, PCT, creatinine, LDH, AST, hypersensitive cardiac troponin I, prothrombin time, D-dimer, and lymphocyte count are helpful in evaluating the severity of the disease and can predict the prognosis of COVID-19." (PMID 37122395, 2023). "A comparison of biomarkers estimated in COVID-19 patients showed that ALT, AST, bilirubin, urea, BUN, and Cl levels were significantly higher in children than in adults, but the levels of total protein, creatinine, Na, and CRP were lower in children in comparison to adult patients." (PMID 37378147, 2023). "Compared with patients who reattended ED but were not admitted, patient who were admitted had a higher mean CRP (54.2 vs 42.1 mg/L), lower lymphocyte count (0.97 vs 1.41 x1000/μL) and earlier median day of COVID-19 illness (7 vs 8 days) at time of initial COVID-19 assessment." (PMID 37437035, 2023). "The primary aim of this study was to prospectively study plasma levels of PSP in a COVID-19 intensive care unit (ICU) population to determine how well PSP performed as a marker of mortality in comparison to other plasma biomarkers, such as C reactive protein (CRP) and procalcitonin (PCT)." (PMID 37391718, 2023). "•No statistical difference in CRP levels of COVID-19 positive vs. negative patients." (PMID 37364815, 2023). "In addition, the results also demonstrate that among the biomarkers evaluated, CRP and AST had the highest number of significant correlations, demonstrating the need to direct attention to this biomarker during the first week of hospitalization for COVID-19." (PMID 38274462, 2023).
COVID-19 (continued). "The maximum levels of C-reactive protein (CRP) and procalcitonin among COVID-19 cases and non-COVID-19 cases were not significantly different (p = 0.125 and p = 0.086), but the levels of CRP ≥ 300 mg/L and procalcitonin ≥ 5 ng/mL are significantly higher in control group (p = 0.05 and p < 0.001)." (PMID 37587143, 2023). "In our study, critical COVID-19 groups also exhibited significant positive correlations of U-CysLT values with several systemic inflammatory markers and parameters, namely with the proinflammatory cytokines IL-6 and TNF-α, with CRP and with total leukocytes, neutrophils, eosinophils and NMR ratio." (PMID 36617343, 2023). "IL-6, neutrophil count, % neutrophils, NLR, PLR, CRP, AST, and urea increased with the severity of the SARS-CoV-2 infection, and the lymphocyte count, % lymphocytes, eosinophil count, % eosinophils, and hemoglobin decreased with the increased severity of COVID-19." (PMID 36838284, 2023). "In addition, we assessed the inflammatory status of patients by monitoring only CRP values without measuring levels of cytokines with a recognized role in COVID-19, such as IL-6." (PMID 37959277, 2023). "Moreover, we found that the CRP and AST biomarkers showed the highest numbers of significant correlations, demonstrating the need to direct attention on these biomarkers during the first week of COVID-19 hospitalization." (PMID 38274462, 2023). "CRP is a marker that is routinely measured in COVID-19 patients in the hospital along with D-dimer and ferritin, the latter of which has not been reported as widely in COVID-19 cases." (PMID 36181766, 2022). "Patients of the APMV2020 group demonstrated faster recovery from symptoms of COVID-19 evident by more and more subjects getting relieved of symptoms in five days, such as cough, myalgia, headache, and anosmia, and reduced serum levels of inflammatory markers like LDH, ferritin, and CRP." (PMID 35783877, 2022). "However, in the plasma of SARS-CoV-2-infected patients we found increased levels of both axes, IL-6/CRP and IL-18/ferritin; however, although IL-6 positively correlated with CRP, IL-18 failed to correlate with ferritin in COVID-19 patients." (PMID 35663992, 2022). "However, in our study population, the increase in FVIIa-AT in COVID-19 patients appeared to be independent of inflammatory markers, namely CRP." (PMID 36428852, 2022). "In conclusion, the increase in CRP, PCT, ESR, ferritin, troponin, D-dimer, LDH, and neutrophil count and the decrease in albumin, PLT, and lymphocyte count are significant in the severe patient group, and it is thought that they can help in determining the severity of COVID-19." (PMID 35950826, 2022). "It was observed that oxygen saturation, WBC count, Neutrophil–lymphocyte ratio, LDH level, CRP level, and ESR level had a significant positive correlation with the transcript levels of TLR3, TLR7, TLR8, and TLR9 in the COVID-19 Group A as well as COVID-19 Group B patients." (PMID 35538443, 2022). "Overproduction of inflammatory cytokines (so-called cytokine storm) is observed in the severe COVID-19 patients, as evidenced by elevated serum levels of proinflammatory cytokines (in particularly, interleukin-6 (IL6) and tumor necrosis factor alpha (TNF)), and C-reactive protein (CRP)." (PMID 36741372, 2022). "Initial and maximum CRP and maximum LDH levels were significantly higher in COVID-19 fatalities compared to those that survived, suggesting that these could be appropriate biomarkers for monitoring COVID-19 patients." (PMID 35893707, 2022). "Patients with mild COVID-19 present with fever, cough, sore throat, fatigue, headache, dyspnea, or myalgia, have normal or decreased leukocyte counts, and might show increased blood levels of ALT, AST, LDH, CK-MB, CRP, and ESR (Chan J. F.-W." (PMID 35664675, 2022).